MTHFD1P1 (methylenetetrahydrofolate dehydrogenase (NADP+ dependent) 1 pseudogene 1)
Synonyms: MTHFDL1; MTHFDP1
Gene: Processed pseudogene on chromosome X (57,392,646 to 57,395,409, reverse strand). Ensembl gene ENSG00000231831.
Diseases named in the same sentence as MTHFD1P1 in open-access papers:
MTHFD1P1 is named in the same sentence as 1 disease in open-access papers, as found by Europe PMC text mining. Sharing a sentence is not in itself a finding about the gene and the disease.
MTHFD1P1 shares sentences with these, for which no sentence is quoted: Alzheimer disease (1 paper).